RNU6-662P (RNA, U6 small nuclear 662, pseudogene)
Gene: Small nuclear RNA gene on chromosome 1 (151,747,597 to 151,747,700, reverse strand). Ensembl gene ENSG00000206980.
Homologues: Orthologues: chimpanzee U6 (98% identical), macaque U6 (90% identical). Paralogues in human: RNU6-748P (88% identical), RNU6-1060P (88% identical), RNU6-199P (87% identical), RNU6-41P (87% identical), RNU6-517P (87% identical), RNU6-1038P (86% identical), RNU6-1152P (86% identical), RNU6-116P (86% identical), RNU6-15P (86% identical), RNU6-19P (86% identical), RNU6-474P (86% identical), RNU6-562P (86% identical), and 1288 more.